ANXA2 (annexin A2)
Diseases named in the same sentence as ANXA2 in open-access papers (continued):
Sharing a sentence is not in itself a finding about the gene and the disease.
tumor (continued). "Besides, the results of tumor microenvironment analysis suggested that ANXA5, STAT1, CD44, CAV1, and ANXA2 expression was positively correlated with the infiltration of B cell, CD8+ T cell, CD4+ T cell, macrophages, neutrophils, and dendritic cells." (PMID 40607003, 2025). "In tumour cells overexpressing S100A10, Src-mediated phosphorylation of ANXA2 is increased, which may be related to S100A10 promoting the translocation of ANXA2 to the plasma membrane." (PMID 40234383, 2025). "Our cell communication analysis suggests that SPOCK1+ CAFs may regulate ANXA2 expression through an autocrine mechanism involving insulin-like growth factor (IGF) signaling, thereby influencing tumor progression." (PMID 40837013, 2025). "Previous studies have shown that ANXA2 and S100A11 aggregate and reseal the plasma membrane at the site of tumour cell membrane damage and that calcium ion efflux is essential in this process, which is consistent with our hypothesis." (PMID 40234383, 2025). "High-ANXA2 was correlated with decreased proportion of granzyme B+ CD8+ T cells (Spearman’s ρ = − 0.40, P = 0.01), and increased TIM-3+ (Spearman’s ρ = 0.43, P < 0.001) and CTLA4+ (Spearman’s ρ = 0.49, P < 0.001) tumor-infiltrating lymphocytes." (PMID 38519766, 2024). "Annexin A2 (ANXA2) play a pivotal role in angiogenesis and tumor angiogenesis." (PMID 38999976, 2024). "The multivariate model included three risk factors: tumor histologic subtype (non-ccRCC or ccRCC), IMDC risk group (favorable, intermediate or poor) and ANXA2 expression (high or low)." (PMID 38519766, 2024). "In addition, we demonstrated the molecular mechanism by which NASP mediates DNA repair through ANXA2 in GBM, and observed the effect of combination treatment with the STAT3 pathway inhibitor, WP1066, and radiotherapy in tumor‐bearing mice models." (PMID 38605477, 2024). "Meanwhile, genes positively correlated with CLDN4 in expression, such as ANXA2, EZR and ELF3, were also discovered in our study, which were also reported to play a role in tumour progression and might explain the role of CLDN4 in a way." (PMID 38629624, 2024). "High expression of ANXA2, TREM2, TTC39A, and GDF15 may lead to a more suppressive tumor microenvironment and enhanced immune escape, thereby reducing the efficacy of immunotherapy." (PMID 39697329, 2024). "In nasopharyngeal carcinoma, the interaction between tumor cells and ANXA2 can activate dendritic-cell-specific ICAM-grabbing non-integrin (DC-SIGN), also known as CD209." (PMID 39057791, 2024). "The silencing of ANXA2 has also been found to increase the drug sensitivity of GC cells to DDP by the decrease in phosphorylation of P38MAPK and AKT, the downregulation of P-gp, MRP1, and Bcl-2, as well as the upregulation of Bax in tumor cells." (PMID 39594718, 2024). "As the expression of ANXA2 and TTK is up-regulated in clinical tumor specimens, and they are both closely related to high tumor stage and poor prognosis, targeting ANXA2 and TTK may be new therapeutic strategies for ESCC." (PMID 38658569, 2024). "In a multivariate Cox regression model including tumor histology, IMDC group and ANXA2 expression." (PMID 38519766, 2024). "Additionally, overexpression of ANXA2 in extracellular vesicles can mediate epithelial–mesenchymal transition (EMT), enhancing the invasiveness of tumor cells." (PMID 39350574, 2024). "By modulating the Src/annexin A2/AKT/mTOR signaling pathway, S100A10 could promote pro-tumor aerobic glycolysis, suppress cell apoptosis, and maintain cell proliferation." (PMID 37892132, 2023). "Moreover, the use of a specific imaging marker targeted to phospho-ANXA2 on a variety of solid tumor types has shown Annexin A2 is highly phosphorylated in the TME, with particular localization at the invasive tumor front." (PMID 37941562, 2023). "The results indicated that ascites-derived GZMK+ TEM cells might serve as an important source of T cells infiltrating into tumor sites and further transit into TEX or ANXA2+ TEM." (PMID 37488416, 2023).
tumor (continued). "Because serum EVs from TNBC patients promoted angiogenesis in an in vivo Matrigel plug assay in an ANXA2-dependent manner, ANXA2-bearing EVs may affect TNBC tumor progression." (PMID 36835116, 2023). "In a recent study, a cyclic octapeptide, LS301, was also found to target both integrin receptors and phosphorylated ANXA2 in the presence of calcium, and the ability of LS301 to emit near‐infrared fluorescence makes it a desirable imaging probe to illuminate tumor margin." (PMID 36453020, 2023). "Given that GZMK+ TEM cells were mostly enriched in ascites, their transitions to tumor-enriched clusters (TEX and ANXA2+ TEM) might happen together with cross-tissue migration." (PMID 37488416, 2023). "ANXA2 was found to have higher expression levels in HCC tissues than that in matched peritumoral tissues, and this higher expression level of ANXA2 represented a shorter tumor-free survival period in the Kaplan-Meyer analysis." (PMID 35747817, 2022). "ANXA2 expression was also found to be co-localized with cells expressing proliferating cell nuclear antigen (PCNA), a known marker of cell proliferation and tumour aggressiveness." (PMID 35204653, 2022). "Depletion of ANXA2 resulted in elevation of cellular ROS upon OS, activation of the ROS-induced pro-apoptotic kinases, JNK, p38, and AKT, and increased sensitivity to ROS-mediated cell damage/death, elevated protein oxidation, and decreased tumor growth." (PMID 36500393, 2022). "Reanalysis of the ARG1-FISH data and spatial plots showed that ARG1-FISH+ cells were also preferentially located within the tumor compartment as opposed to outside of it, placing ANXA2 protein and ARG1 transcript in a similar anatomical location." (PMID 36377658, 2022). "Interestingly, exosome analysis shows higher expression of exosomal-Annexin 2 (exo-AnxA2) in the sera of AA women with TNBC indicating its potential role in angiogenesis and tumor promotion." (PMID 34889737, 2021). "Furthermore, the relationship of ANXA2 with OSCC patients’ clinical features were analyzed and the results indicated that the expression of ANXA2 was correlated with the TNM stage, tumor differentiation and lymph node metastasis (P < 0.05)." (PMID 33658625, 2021). "BD treatment may induce ANXA2, TGFI, FN1, HSP90B1 down-regulation, and FRK up-regulation to inhibit tumor metastasis by regulating autophagy, hypoxia, β-catenin, and STAT3 signaling pathways." (PMID 34685653, 2021). "The results in the present study show that ANXA2 is significant for the development and survival of OSCC and plays a pivotal role in tumor proliferation, migration, and invasion of OSCC cells, which should be concerned by clinical and considered as a potential target of OSCC therapy." (PMID 33658625, 2021). "Accordingly, ANXA2 expression was significantly downregulated in tumor vs. normal tissue (p < 0.0001) and in tumor vs. normal adjacent (p < 0.0001)." (PMID 32197509, 2020). "Our analysis of AnxA2 phosphorylation in clinical samples further confirmed that the phosphorylation of AnxA2 at Tyr23 was high in tumor tissues of TNBC patients compared to matched adjacent non-tumorigenic breast tissues." (PMID 33374917, 2020). "More importantly, priming with the Lm-ANXA2 treatment prior to administration of anti-PD-1 antibodies increased cure rates in the implanted PDAC model and resulted in objective tumor responses and prolonged survival in the genetically engineered spontaneous PDAC model." (PMID 31113479, 2019). "We first found that the concurrent combination of Lm-ANXA2 and anti-PD-1 antibody (data not shown) did not have enhanced anti-tumor activity comparing Lm-ANXA2 alone." (PMID 31113479, 2019). "There was a statistically significant increase in maximum tumor response in treatment with the combination therapy of Lm-ANXA2 + anti-PD-1 blockade when compared to no treatment (p = 0.022) and to treatment with Empty Lm alone (p = 0.027)." (PMID 31113479, 2019).
tumor (continued). "We examined the interaction among HE4, ANXA2 and MMP2 in various malignant tumor cell lines and the tool cell line HEK293, according the results, it was inferred that HE4, ANXA2, and MMP2 might form a protein complex." (PMID 31210752, 2019). "ES-2 has high expression of both HE4 and ANXA2, which indicated that a concomitant high expression of HE4 and ANXA2 might promote the adhesion behavior of tumor cells." (PMID 31210752, 2019). "Next, one representative GBM tissue exacted from a GBM patient during surgery was examined by FISH double staining and the results showed that ANXA2 and miR155HG were both significantly expressed in dense tumor tissues, but not in loose normal brain tissue." (PMID 30898167, 2019). "In this study, we found that only the sequential combination of Lm-ANXA2 followed by anti-PD-1 antibody, not the concurrent combination of Lm-ANXA2 and anti-PD-1 antibody (data not shown), had enhanced anti-tumor activity compared to Lm-ANXA2 alone." (PMID 31113479, 2019). "Moreover, the molecular interaction of ANXA2 and DC-SIGN triggers immunosuppression, which results in tumor immune escape." (PMID 29598816, 2018). "Immunohistochemical analysis of human GBM samples confirmed higher expression levels of annexin A2 in tumor cells clustered around neovasculatures, but not in diffusely invasive tumor cells." (PMID 29642503, 2018). "We found that ANXA2 is overexpressed in CRC samples, particularly in invasive tumours." (PMID 30050103, 2018). "This indicates that AnxA2 expression is necessary in both the TME and on tumor cells." (PMID 29290958, 2017). "However, the growth impairment of the annexin A2-depleted tumors was rescued by the administration of the antioxidant compound, N-acetyl cysteine (NAC), in the mice during tumor formation." (PMID 26682014, 2016). "miR-206 functions as a tumor suppressor in pancreatic cancer by inhibiting metastatic cell invasion and overall tumor growth and proliferation through the targeting of oncogenic K-Ras, an initiator of PDAC and of ANXA2, a regulator of extra cellular matrix degradation." (PMID 27240340, 2016). "Annexin A2 could also inhibit the trafficking of CD147-harboring membrane microvesicles and enhance the migration and invasion potential of tumor cells." (PMID 27121050, 2016). "Our data suggest that immunogenic activity is absent or is overridden by other potentially tumor-promoting functions of ANXA2, or by tumor-derived immune suppressive mechanisms such as regulatory T cells or myeloid-derived suppressor cells." (PMID 26885373, 2016). "As expected, the expression levels of STAT1 and MX1 were up-regulated in OSCC tumors (7/9 and 9/9 for STAT1 and MX1, respectively), whereas the levels of ANXA2 were similar between the tumor tissues and the adjacent normal tissues." (PMID 26110569, 2015). "Among all genes tested, ONECUT2, IGF2BP1, and ANXA2 were aberrantly upregulated in tumor tissues compared to non-tumor tissues." (PMID 26547929, 2015). "Overexpression of ANXA2 in tumor tissue over adjacent noncancerous epithelial cells is positively correlated with tumor size and tumor recurrence, but negatively correlated with tumor differentiation grades." (PMID 24591759, 2014). "Even though two UTUC tumor tissues and most normal tissues did not express annexin A3, both annexin A2 and annexin A3 showed stronger expression in UTUC urine samples than those in the urine of healthy control." (PMID 24884814, 2014). "Pathological analysis of the tumours showed no clear morphological alterations and the distribution of ANXA2 was mainly localised to the cell membrane in the shRNA group and the cell membrane and cytoplasm in the mock and negative groups." (PMID 24348815, 2014). "Proteomic analysis of PDAC patient samples revealed that annexin A2 is overexpressed in 88.6% of tumor tissues and only 34.2% of non-tumorous pancreatic tissues." (PMID 23519104, 2013).
tumor (continued). "This could implicate the involvement of annexin A2 in epithelial-mesenchymal transition (EMT) and tumor metastasis." (PMID 23519104, 2013). "Our results show that knocking down the expression of ANXA2 in HCC cells inhibits the migratory and invasive potential of these tumor cells and significantly attenuates the production of MMPs by fibroblasts, which were previously reported to be involved in human hepatic tumorigenesis and metastasis." (PMID 23950866, 2013). "Whereas the two tumor samples where we did not observe up-regulation of reduced ANXA2 showed increased total protein oxidation." (PMID 22185818, 2011). "There is evidence of a relationship between proteases and extracellular matrix (ECM) proteins through ANXA2 whereby ANXA2 may facilitate the reorganization of the ECM in physiological and pathological processes such as tumor invasion." (PMID 22040021, 2011). "For example, Annexin A2 (ANXA2) plays a key role in invasion, metastasis, angiogenesis, and cell proliferation, while CD44, a receptor for hyaluronic acid, osteopontin, and matrix metalloproteinases, contributes to tumor growth, cell motility, and angiogenesis." (PMID 40344389, 2025). "Although several studies have demonstrated the roles of ANXA2 in tumour progression, no systematic review has elucidated the roles of ANXA2 with respect to antiapoptotic effects, how ANXA2 responds to apoptotic stress signals, or its relationship with immune escape." (PMID 40234383, 2025). "Thus, we hypothesize that CAF+SPOCK1 cells may upregulate ANXA2 expression and phosphorylation through autocrine IGF signaling, further promoting EMT and tumor progression." (PMID 40837013, 2025). "Therefore, we speculate that nuclear ANXA2 may promote DNA damage repair by inhibiting PARP1 cleavage and increasing tumour cell survival." (PMID 40234383, 2025). "Notably, TRIM31 (logFC = 1.14), ANXA1 (logFC = 1.05), GBP1 (logFC = 1.01), BIRC3 (logFC = 0.99), APOL1 (logFC = 0.97), IL18 (logFC = 0.94), ANXA2 (logFC = 0.89), BHLHE40 (logFC = 0.83), and EPHA2 (logFC = 0.75) exhibited significant upregulation in tumour tissues." (PMID 38254861, 2024). "CTSB can also bind annexin A2 on the cell surface 115 and is involved in the activation of binding proteins in discrete regions of the extracellular space, which may explain the role of CTSB in tumor invasion and metastasis." (PMID 37576397, 2023). "The plasminogen receptors ENO1, histone H2B, Plg-RKT, ANXA2 and S100A10 have been shown to be expressed at the cell surface of human monocytes/macrophages, where they are involved in plasminogen activation and play an important role in the recruitment and migration of macrophages to tumour sites." (PMID 35204653, 2022). "The tumour ECM is remodelled at the protein level in MGUS and MM to allow development of a permissive microenvironment with two ECM-affiliated proteins, Annexin A2 (ANXA2) and Galectin-1 (LGALS1), more abundant in MM with high expression associated with inferior OS." (PMID 34556161, 2021). "Person’s chi-square test indicated that the combined expression of ANXA2 and GPC1 was dramatically associated with age (P < 0.001), WHO grade (P = 0.005), recurrence (P < 0.001), and survival status (P < 0.001) but not with gender or tumor location." (PMID 33712571, 2021). "Likewise, AnxA2-mediated NFκB signaling contributed to tumourigenicity in xenograft models for glioblastoma multiforma (GBM), with AnxA2 depletion strongly inhibiting GBM tumour growth and improving survival." (PMID 33810523, 2021). "Further, CRC tumor expresses obviously higher levels of lncRNA LINC00659 than do normal cells, and the mechanism herein illustrates that exosomal LINC00659 functioning as a ceRNA mediates miR-342-3p/ANXA2 axis, thereby promoting cell proliferation, invasion, migration and EMT in CRC." (PMID 33407563, 2021).
tumor (continued). "S100A4, cathepsin B, cyclin B1, Annexin A2, S100A10, TRIM21, 14-3-3 ζ/δ, and Ezrin may hence participate in tumor invasion depending on the grade of human CRCs, and protein upregulation during lymph node metastasis also suggests a positive correlation with metastasis in human CRCs." (PMID 32154176, 2020). "In addition to their role in regulating tumor progression, APLNR is mainly involved in the neuroactive ligand-receptor interaction and vascular development, while ANXA2 mainly participates in the modulation of depressive behavior and signal transduction pathways." (PMID 33123575, 2020). "Additionally, we also found some proteins potentially having anti-tumor properties, such as annexin A2 (ANXA2) and vascular cell adhesion molecule 1 (VCAM1), but have not been used in cancer drug development." (PMID 33287876, 2020). "In HCC, the expression of ANXA2 was higher in tumor tissue than in nontumor tissue." (PMID 30881525, 2019). "Finally, we determined Annexin A2 expression in clinical samples using immunohistochemistry analysis in 152 NSCLC tissues and 36 adjacent normal tissues and found that Annexin A2 was overexpressed in tumor samples than adjacent normal tissues." (PMID 28886730, 2017). "The high affinity aptamer, although not initially planned to bind to the post-SELEX identified tumor biomarker Annexin A2, could however be a promising tool for biomedical applications." (PMID 28635657, 2017). "The expression levels of ONECUT2, IGF2BP1, and ANXA2 were significantly upregulated in tumor tissues compared with non-tumor tissues, which suggested that they might play an oncogenic role in HCC development." (PMID 26547929, 2015). "By contrast, ANXA2 levels do not correlate with tumour size and AFP levels." (PMID 24348815, 2014). "Western blotting analysis and immunohistochemistry of tumor tissues and normal tissues from patients with UTUC were carried out to further verify five possible UTUC biomarkers, including zinc-alpha-2-glycoprotein, calreticulin, annexin A2, annexin A3 and haptoglobin." (PMID 24884814, 2014). "Similar to annexin A2, we for the first time showed that the over-expression of annexin A3 in the urine and tumor tissues of patients with UTUC in comparison with healthy controls while annexin A3 was over-expressed in the tumor areas of eight tumor/adjacent normal tissue pairs (61.5%)." (PMID 24884814, 2014). "To study the possible interaction between ANXA2 and CD147 and to explore the hypothesis that ANXA2 is involved in the shedding of CD147-harboring microvesicles from tumor cells, we performed immunofluorescent double-labeling on SMMC-7721 and FHCC-98 cell slides." (PMID 23950866, 2013). "Consequently, if the growth deficit observed in the annexin A2-depleted tumours was due to decreased plasmin activation, the addition of NAC would not have reversed the phenotype and restored the growth of annexin A2-depleted tumours, as observed." (PMID 23434659, 2013). "This study identifies a unique AR-positive tumor-associated macrophages (AR+ TAMs) subpopulation, enriched in ENZ-resistant patients and correlated with poor prognosis, which acquires functional AR protein not through endogenous expression but via ANXA2-dependent phagocytosis of tumor cells." (PMID 41990247, 2026). "It should be noted that Lm-ANXA2 alone, or with IgG isotype control, did not appear to consistently result in long term survival greater than 120 days in this hemispleen mouse model, presumably dependent on the variation of tumor burden established in each individual mouse." (PMID 31113479, 2019). "However, we have recently established that S100A10, and not annexin A2, is responsible for not only promoting the reported macrophage plasminogen-mediated matrix invasion and degradation but also the infiltration of tumor-promoting macrophages into tumor sites." (PMID 23519104, 2013).